MYOM1 (myomesin 1)
Description:
Major component of the vertebrate myofibrillar M band. Binds myosin, titin, and light meromyosin. This binding is dose dependent.
Synonyms: SKELEMIN
Tractability: Small molecule: it has a binding pocket of medium quality.
Gene: Protein-coding gene on chromosome 18 (3,066,693 to 3,220,126, reverse strand). Ensembl gene ENSG00000101605.
Subcellular location: Cytoplasm, myofibril, sarcomere, M line
Gene Ontology:
Molecular function: identical protein binding; kinase binding; protein binding; protein homodimerization activity; structural constituent of muscle
Biological process: positive regulation of cAMP/PKA signal transduction; positive regulation of gene expression; sarcomere organization; extraocular skeletal muscle development
Cellular component: M band; striated muscle myosin thick filament; sarcomere
Genetic constraint (gnomAD): Loss-of-function variants: 155 observed, 192.39 expected, observed/expected ratio (o/e) 0.81, 90% interval 0.71 to 0.92. The upper end of that interval is the gene's LOEUF score, 0.92, which puts it in group 3 of 6, group 1 being the genes least tolerant of losing a copy. Missense variants: 1,910 observed, 2,083.6 expected, observed/expected ratio (o/e) 0.92, 90% interval 0.88 to 0.95. Synonymous variants: 745 observed, 783.23 expected, observed/expected ratio (o/e) 0.95, 90% interval 0.89 to 1.01.
Gene-disease validity (ClinGen):
ClinGen rates the evidence that MYOM1 causes each of these diseases.
hypertrophic cardiomyopathy (autosomal dominant): Disputed. A condition in which the myocardium is hypertrophied without an obvious cause.
Homologues: Orthologues: chimpanzee MYOM1 (97% identical), macaque MYOM1 (96% identical), dog MYOM1 (89% identical), rat Myom1 (88% identical), pig MYOM1 (87% identical), mouse Myom1 (86% identical), guinea pig MYOM1 (85% identical), rabbit MYOM1 (82% identical), tropical clawed frog myom1 (64% identical), zebrafish myom1b (57% identical), zebrafish myom1a (49% identical), Caenorhabditis elegans C34F6.10 (12% identical), and 1 more. Paralogues in human: MYOM2 (40% identical), MYOM3 (34% identical), MYBPC3 (15% identical), OBSL1 (14% identical), MYBPC1 (13% identical), MYBPC2 (13% identical), FNDC3B (13% identical), FNDC3A (13% identical), IGSF22 (12% identical), MYBPH (6% identical), MYBPHL (5% identical).
Diseases named in the same sentence as MYOM1 in open-access papers:
MYOM1 is named in the same sentence as 22 diseases in open-access papers, as found by Europe PMC text mining. Sharing a sentence is not in itself a finding about the gene and the disease. The quoted sentences say what the papers report.
cardiomyopathy (6 papers, 2017 to 2023). A disease of the heart muscle or myocardium proper. "Furthermore, a panel of 108 cardiomyopathy and arrhythmia-associated genes, including only MYOM1, was screened in 24 patients with restrictive cardiomyopathy." (PMID 33033063, 2020). "This loss of M-band MYOM1 was also observed in CMs harboring HCM-associated ALPK3 variants and was highly disorganized in a mouse model of ALPK3 cardiomyopathy." (PMID 39196058, 2023).
Arrhythmia (3 papers, 2020 to 2021). Any cardiac rhythm other than the normal sinus rhythm. "We found that knockout of MYOM1 resulted in a decrease in the contractility of cardiomyocytes, but no occurrence of arrhythmia, regardless of under basal conditions or stressed conditions, indicating that the structural gene MYOM1 mainly affects myodynamia, but has little effect on myoelectricity." (PMID 33452765, 2021).
dilated cardiomyopathy (2 papers, 2022 to 2024). Cardiomyopathy which is characterized by dilation and contractile dysfunction of the left and right ventricles. "The clinical significance of the sequence changes found in MYOM1 is currently under investigation, especially in patients with hypertrophic or dilated cardiomyopathy or in patients with sudden cardiac death." (PMID 39139851, 2024). "Previous studies have shown that variations in MYOM1 and MYOM3 could cause cardiac abnormalities, such as hypertrophic cardiomyopathy and dilated cardiomyopathy." (PMID 35872890, 2022).
hypertrophic cardiomyopathy (2 papers, 2022 to 2024). "Although primarily known for its role in muscle structure, MYOM1 has been implicated in cardiovascular diseases, particularly hypertrophic cardiomyopathy (HCM) where mutations in the MYOM1 gene have been associated with abnormal thickening of the heart muscle." (PMID 38596466, 2024).
adenocarcinoma of the breast (1 paper, 2017). "CELF1 has been found involved in previous fusions with five different partners: with MTCH2 and MYOM1 in SCC and adenocarcinoma of the lung, respectively; with LUZP2 and ARFGAP2 in adenocarcinoma of the breast; and with BBOX1 in grade I-II astrocytoma of the brain." (PMID 28186972, 2017).
chronic heart failure (1 paper, 2021). "In addition, it has been reported that myomesin (encoded by both MYOM1 and MYOM2) protein levels decrease in acute ischemia and in chronic heart failure." (PMID 34158603, 2021).
endometriosis (1 paper, 2022). The growth of functional endometrial tissue in anatomic sites outside the uterine body. "In this study, we screened four characteristic genes of endometriosis (ACLY, PTGFR, ADH1B, and MYOM1) by using the full transcriptome sequencing data of clinical samples and public database resources." (PMID 35938015, 2022). "Hence, four genes were defined as characteristic genes for endometriosis by overlapping the genes derived from these two algorithms, including ACLY, PTGFR, ADH1B, and MYOM1." (PMID 35938015, 2022).
Myotonia (1 paper, 2025). An involuntary and painless delay in the relaxation of skeletal muscle following contraction or electrical stimulation. "Notably, there are a few genes that are misspliced in DM1, and have been linked to a definitive symptomatic outcome, that are misspliced neither in FSHD nor EDMD, namely CLCN1, ATP2A1/2 and MYOM1, of which the CLCN1 missplicing results in the most unique feature of DM1: myotonia." (PMID 40149583, 2025).
Tetralogy of Fallot (1 paper, 2024). A congenital cardiac malformation comprising pulmonary stenosis, overriding aorta, ventricular septum defect, and right ventricular hypertrophy. "Overexpression of MYOM1 in myocardium has also been reported in patients with tetralogy of Fallot, potentially linked to impaired cardiac function." (PMID 38596466, 2024).
tumor (3 papers, 2012 to 2023). "Moreover, the mutations ALPK2.R136S, CHST9.S122N, FAM38B.V2463, LAMA1.S1577A, LAMA1.K2002E, MYOM1.T215M, SERPINB10.R246C and SLC14A2.A880T were found in all three tumor samples and shared a similar frequency profile." (PMID 23892400, 2013). "By comparing tumor versus non-transgenic tissue the genes Mthfd1, Myom1 and Ppp2r5c showed change in direction of gene expression." (PMID 22815814, 2012). "However, when comparing tumor versus transgenic tissue gene Kif26b showed a change in direction and when comparing tumor versus non-transgenic tissue the genes Mthfd1, Myom1 and Ppp2r5c equally differed in direction of gene expression." (PMID 22815814, 2012).
myopathies (2 papers, 2021 to 2024). "However, little is known about its biological function, causal relationship and mechanisms underlying the MYOM1‐related myopathies (especially in the heart)." (PMID 33452765, 2021). "Thus, we generated an MYOM1−/− hESCs (H9) cell line with CRISPR/Cas9 system, which can be continuously subcultured, and myocytes differentiated from it provide a useful model to study biological functions of MYOM1 and the pathological mechanisms underlying MYOM1‐related myopathies." (PMID 33452765, 2021).
cancer (1 paper, 2017). A tumor composed of atypical neoplastic, often pleomorphic cells that invade other tissues. "In contrast, lower expression of the downregulated genes (such as SCARA5, MYOM1, NKAPL, PEG3, USP2, SLC5A7 and HMGCLL1) in various cancers is associated with poor clinical outcomes in cancer." (PMID 28427185, 2017). "More importantly, we found a number of genes commonly dysregulated in various cancers such as PLP1, MYOM1, NKAPL and USP2 which were investigated in few cancer related studies, and thus represent our novel findings." (PMID 28427185, 2017). "We identified consistently upregulated genes (such as E2F1, EZH2, FOXM1, MYBL2, PLK1, TTK, AURKA/B and BUB1) and consistently downregulated genes (such as SCARA5, MYOM1, NKAPL, PEG3, USP2, SLC5A7 and HMGCLL1) across various cancers." (PMID 28427185, 2017). "However, few studies have shown that PLP1, MYOM1, NKAPL, and USP2 were consistently downregulated in various cancers." (PMID 28427185, 2017).
MYOM1 also shares sentences with these, for which no sentence is quoted: adenocarcinoma of the lung (1 paper); arthrogryposis (1); astrocytoma of the brain (1); atherosclerosis (1); cardiovascular diseases (1); dilatation (1); lung carcinoma (1); myopia (1); Obesity (1); restrictive cardiomyopathy (1).